SLC29A3 (solute carrier family 29 member 3)
Description:
Uniporter that mediates the facilitative transport of nucleoside across lysosomal and mitochondrial membranes. Functions as a non-electrogenic Na(+)-independent transporter. Transport activity is pH-dependent and enhanced under acidic conditions, consistent with localization to acidic intracellular compartments. Protons are not cotransported but likely modulate transport by altering the ionization state of the transporter which dictates its conformation, thereby regulating substrate permeability. May direct the nucleoside transport from lysosomes to cytosol or cytosol to mitochondria to facilitate nucleic acid salvage pathways. Transports nucleosides (adenosine, guanosine, uridine, thymidine, cytidine and inosine), deoxynucleosides (deoxyadenosine, deoxycytidine), purine nucleobases (adenine, guanine) and pyrimidine nucleobases (uracil). Also capable of transporting monoamine neurotransmitters dopamine, serotonin, noradrenaline and tyramine, as well as ATP. Mediates nucleoside export from lysosomes in macrophages, thereby regulating macrophage function and number (By similarity). Also functions as a lysosomal urate exporter, contributing to intracellular urate disposal. Regulates inflammasome activation via dual roles in urate and adenosine transport.
Synonyms: hENT3; ENT3; FLJ11160; HCLAP; HJCD; PHID
Tractability: Small molecule: it belongs to a druggable protein family. Antibody: UniProt places it where antibodies can reach, with high confidence; UniProt predicts a signal peptide or a membrane-spanning region; its Gene Ontology location is reachable by antibodies, with medium confidence. PROTAC: its protein half-life has been measured.
Gene: Protein-coding gene on chromosome 10 (71,319,259 to 71,381,423, forward strand). Ensembl gene ENSG00000198246.
Subcellular location: Lysosome membrane; Late endosome membrane; Mitochondrion membrane; Cell membrane
Subcellular location (Human Protein Atlas): Golgi apparatus; Vesicles
Pathways (Reactome):
Disease: Defective SLC29A3 causes histiocytosis-lymphadenopathy plus syndrome (HLAS)
Drug ADME: Ribavirin ADME
Transport of small molecules: Transport of nucleosides and free purine and pyrimidine bases across the plasma membrane
Gene Ontology:
Molecular function: cytidine transmembrane transporter activity; guanine transmembrane transporter activity; monoamine transmembrane transporter activity; neurotransmitter transmembrane transporter activity; nucleobase transmembrane transporter activity; nucleoside transmembrane transporter activity; protein binding; transmembrane transporter activity; uracil transmembrane transporter activity; urate transmembrane transporter activity; uridine transmembrane transporter activity
Biological process: adenosine transport; cytidine transport; guanine transmembrane transport; inosine transport; nucleobase transport; nucleoside transmembrane transport; nucleoside transport; purine nucleobase transmembrane transport; pyrimidine nucleobase transmembrane transport; uracil transmembrane transport; uridine transmembrane transport; xenobiotic metabolic process; neurotransmitter transport; urate transport
Cellular component: Golgi apparatus; late endosome membrane; lysosomal membrane; mitochondrial membrane; plasma membrane; mitochondrial outer membrane; membrane
Genetic constraint (gnomAD): Loss-of-function variants: 19 observed, 29.89 expected, observed/expected ratio (o/e) 0.64, 90% interval 0.44 to 0.93. The upper end of that interval is the gene's LOEUF score, 0.93, which puts it in group 3 of 6, group 1 being the genes least tolerant of losing a copy. Missense variants: 586 observed, 641.79 expected, observed/expected ratio (o/e) 0.91, 90% interval 0.85 to 0.98. Synonymous variants: 258 observed, 280.56 expected, observed/expected ratio (o/e) 0.92, 90% interval 0.83 to 1.02.
Gene-disease validity (ClinGen):
ClinGen rates the evidence that SLC29A3 causes each of these diseases.
H syndrome (autosomal recessive): Definitive. A systemic inherited histiocytosis, with characteristic cutaneous findings accompanying systemic manifestations.
Homologues: Orthologues: chimpanzee SLC29A3 (99% identical), macaque SLC29A3 (95% identical), dog SLC29A3 (80% identical), guinea pig SLC29A3 (76% identical), mouse Slc29a3 (74% identical), rat Slc29a3 (72% identical), rabbit SLC29A3 (69% identical), zebrafish slc29a3 (39% identical), Drosophila melanogaster Ent2 (25% identical), Caenorhabditis elegans ent-1 (23% identical), Caenorhabditis elegans ent-3 (23% identical), Caenorhabditis elegans ent-7 (23% identical), and 4 more. Paralogues in human: SLC29A1 (31% identical), SLC29A2 (29% identical), SLC29A4 (25% identical).
Diseases named in the same sentence as SLC29A3 in open-access papers:
SLC29A3 is named in the same sentence as 71 diseases in open-access papers, as found by Europe PMC text mining. Sharing a sentence is not in itself a finding about the gene and the disease. The quoted sentences say what the papers report.
H syndrome (35 papers, 2010 to 2026). "H syndrome is a constellation of symptoms caused by mutations in the SLC29A3 gene, inherited in an autosomal recessive pattern." (PMID 41531690, 2026). "H syndrome (HS) is a rare autosomal recessive histiocytosis caused by biallelic mutations of the SLC29A3 gene." (PMID 41953517, 2026). "Mutations in the SLC29A3 gene have been linked to H syndrome and pigmented hypertrichosis with insulin-dependent diabetes mellitus (PHID), both autosomal recessive disorders." (PMID 40426715, 2025). "The aim of this study is to present two Iranian patients with H syndrome and to describe a novel start-loss mutation in SLC29A3 gene." (PMID 38965556, 2024). "H syndrome is an autosomal recessive disorder caused due to biallelic mutation in SLC29A3 gene that encodes hENT3." (PMID 40092871, 2024). "Our study contributes to the expanding body of evidence supporting the association between mutations in the SLC29A3 gene and H syndrome." (PMID 38965556, 2024). "The H syndrome is caused by the presence of mutations in both alleles of the SLC29A3 gene, which is located on chromosome 10q22 and encodes the hENT3 protein." (PMID 38965556, 2024). "H syndrome can arise from various types of mutations in the SLC29A3 gene, including nonsense, missense, compound (involving multiple genetic alterations), or deletion mutations." (PMID 38965556, 2024). "H Syndrome, also known as Histiocytosis-Lymphadenopathy Plus Syndrome, is part of a range of recessive clinically related disorders due to biallelic pathogenic variants of the Solute Carrier Family 29 Member 3 (SLC29A3) gene (OMIM # 602,782)." (PMID 38263041, 2024). "Mutations in SLC29A3 (10q22.2), which codes for the human equilibrative nucleoside transporter-3 (hENT3), the cause of the uncommon autosomal recessive condition known as H syndrome, lead to hENT3’s functions being compromised." (PMID 38093297, 2023). "In the participant with the SLC29A3 variant causing H-syndrome, the genetic diagnosis was crucial for correct management." (PMID 37897565, 2023). "Germline mutations in solute carrier family 29 member 3 (SCL29A3) have been described in hereditary syndromes including H-syndrome and Faisalabad syndrome with the two diseases displaying findings compatible with RDD." (PMID 37790150, 2023). "The H syndrome is an autosomal recessive disorder caused by bi‐allelic mutations in the SLC29A3 gene that encodes ENT3 (equilibrative nucleoside transporter 3), a nucleoside transporter protein." (PMID 36545557, 2022). "Homozygous carriers of SLC29A3 mutation were reported to have the rare H syndrome characterized by pigmented hypertrichotic dermatosis, insulin-dependent diabetes and neuroendocrine dysfunction." (PMID 34630320, 2021). "The present study emphasizes the previously reported intra-familial clinical heterogeneity among Tunisian patients with overlapping features of SLC29A3 disorders (Familial RDD/H syndrome) even in patients who share the same SLC29A3 mutation." (PMID 34657628, 2021). "RDD is also associated with the H syndrome (SLC29A3 gene), Hodgkin disease, acute leukemia, sarcoma, and immunologic/IgG4 syndrome." (PMID 33849657, 2021). "Biallelic mutations in SLC29A3 cause histiocytosis-lymphadenopathy plus syndrome, also known as H syndrome (HS)." (PMID 33284430, 2021). "The first condition to be associated with recessive mutations in the SLC29A3 gene was the H syndrome." (PMID 34657628, 2021). "The present study highlights a remarkable intrafamilial phenotypic variability of SLC29A3 disorder among 5 members of a Tunisian family harboring the same mutation in the SLC29A3 gene and presenting with overlapping features of H syndrome and Familial RDD." (PMID 34657628, 2021).
H syndrome (continued). "In 2008, three single-nucleotide changes in SLC29A3 (1279 G > A, 1309 G > A, 1045delC) were reported as causative for an autosomal-recessive gonodermatosis called ‘H syndrome’5." (PMID 31270333, 2019). "Coincidentally, around the time our work was published, another group investigated a case of H Syndrome that arose from a novel mutation (Glu447Lys) in the SLC29A3 gene." (PMID 28985132, 2018). "Mutations in the SLC29A3 gene have been implicated in various related syndromes in humans: ‘H syndrome’, PHID, FHC and SHML." (PMID 22238637, 2012). "We then identified germline SLC29A3 mutations in patients diagnosed with syndromic forms of histiocytosis (Faisalabad histiocytosis and familial RDD/SHML (fRDD))." (PMID 20140240, 2010). "Comparison of clinical features of families with SLC29A3 mutations from this report and those reported with H syndrome and PHID syndrome." (PMID 20140240, 2010). "As SLC29A3 variants cause an autoinflammatory H-syndrome phenotype, the presence of autoantibodies suggests this may not be coincidental but part of the autoinflammatory process." (PMID 40746173, 2026). "Mutations in SLC29A3 can lead to impaired phagocytosis, which in turn causes an excessive inflammatory response and abnormal proliferation of histiocytes, contributing to the clinical features observed in H syndrome." (PMID 38965556, 2024). "H Syndrome is a rare genetic condition caused by biallelic pathogenic variants in the SLC29A3 gene." (PMID 38263041, 2024). "However, due to the fact that H syndrome encompasses the majority of these clinical features and all of these disorders share identical mutations in the SLC29A3 gene, they are now considered to be the same entity." (PMID 38965556, 2024). "The presence of different mutation types in SLC29A3 may partially explain the extensive variability observed between different families affected by H syndrome." (PMID 38965556, 2024). "Mutations in the SLC29A3 gene, including missense, nonsense, and deletion mutations, lead to various medical manifestations ranging from mild to severe, which are known as the same entity termed H syndrome." (PMID 38965556, 2024). "Pathogenic variants in SLC29A3 cause histiocytosis–lymphadenopathy plus syndrome or H-syndrome." (PMID 37897565, 2023). "Loss-of-function mutations in SLC29A3 cause monogenic diseases, including H syndrome, Faisalabad histiocytosis, pigmented hypertrichosis with insulin-dependent diabetes mellitus syndrome, and familial Rosai-Dorfman disease." (PMID 37462944, 2023). "Homozygous mutations in SLC29A3 confirmed the diagnosis of H syndrome in both cases." (PMID 37638031, 2023). "The nucleoside transport capabilities of the human equilibrative nucleoside transporter-3 (hENT3) are disrupted by mutations in SLC29A3 (10q22.2), which are genes for the nucleoside transporter and are the cause of the unusual autosomal recessive disease known as H syndrome." (PMID 38093297, 2023). "SLC29A3 germline mutation is associated with familial or Faisalabad histiocytosis and H syndrome." (PMID 36358690, 2022). "Germline mutations in SLC29A3 (at 10q23), which is associated with H syndrome (histiocytosis-lymphadenopathy plus syndrome), Faisalabad histiocytosis, and pigmented hypertrichotic dermatosis with insulin-dependent diabetes, have been found in cases of familial RDD." (PMID 36358690, 2022). "Although the phenotypes of Familial RDD and H syndrome are distinguished by a minimal clinical overlap, both may be associated with identical mutations of c.307delTT, c.1309G > A and c.1088G > A in SLC29A3." (PMID 34657628, 2021). "The medical history of our family highlights a wide phenotypic variability characterizing H syndrome, in terms of organ involvement and disease severity, and confirms that patients carrying the same mutation in the SLC29A3 gene may display different symptoms." (PMID 34657628, 2021).
H syndrome (continued). "Germline mutations in SLC29A3 have been reported in rare patients with a wide range of overlapping clinical features and inherited disorders including H syndrome, pigmented hypertrichosis with insulin-dependent diabetes, and Faisalabad histiocytosis." (PMID 22238637, 2012). "The identification of SLC29A3 mutations as the molecular basis for a familial form of syndromic histiocytosis (FHC/RDD) confirms a direct link between Faisalabad histiocytosis and Rosai-Dorfman disease and links these disorders to other SLC29A3-associated phenotypes." (PMID 20140240, 2010). "Mutations in the SLC29A3 gene, which encodes the nucleoside transporter hENT3, have been implicated in syndromic forms of histiocytosis including H syndrome, pigmented hypertrichosis with insulin-dependent diabetes, Faisalabad histiocytosis and Familial Rosai–Dorfman disease (RDD)." (PMID 34657628, 2021). "Interestingly, a recent study has described germline SLC29A3 mutations in H syndrome." (PMID 20140240, 2010). "The spectrum of SLC29A3-related diseases also known as histiocytosis-lymphadenopathy plus syndrome includes Faisalabad histiocytosis, Rosai–Dorfman disease, H syndrome, and pigmented hypertrichotic dermatosis with insulin-dependent diabetes (PHID)." (PMID 40282877, 2025). "The molecular analysis of diseases related to SLC29A3 is crucial in understanding the range of variability and raising awareness of H syndrome, with the ultimate goal of facilitating early diagnosis and appropriate treatment." (PMID 38965556, 2024). "The diverse array of genetic alterations in SLC29A3 can contribute to the wide range of clinical presentations and manifestations observed in individuals with H syndrome." (PMID 38965556, 2024). "Other syndromes caused by SLC29A3 mutations include pigmented hypertrichotic dermatosis with insulin-dependent diabetes (PHID), Faisalabad histiocytosis (FH), and Familial Rosai–Dorfman Disease." (PMID 35955904, 2022). "H syndrome, also known as histiocytosis‐lymphadenopathy plus syndrome or PHID, is a rare genetic condition caused by mutations in the SLC29A3 gene." (PMID 36545557, 2022). "H syndrome, also known as histiocytosis‐lymphadenopathy plus syndrome or PHID, is a rare genetic condition caused by mutations in the SLC29A3 gene which encodes the human equilibrative nucleoside transporter (hENT3) protein." (PMID 36545557, 2022). "In contrast with H syndrome, the Familial RDD phenotype was only twice associated with mutations in the SLC29A3 gene." (PMID 34657628, 2021). "Previous studies have described other diseases caused by mutations in the SLC29A3 gene, such as pigmented hypertrichosis dermatosis with insulin-dependent diabetes syndrome (PHID), Faisalabad histiocytosis, and familial Rosai Dorfman disease, among others." (PMID 34193201, 2021). "Several syndromes, including the H syndrome and the pigmented hypertrichosis with insulin dependent diabetes (PHID) syndrome have been associated with mutations in the SLC29A3 gene." (PMID 25713533, 2015). "The child with a mutation in SLC29A3 had no clinical manifestations attributed to H syndrome." (PMID 31276222, 2019).
Histiocytosis (14 papers, 2010 to 2026). An excessive number of histiocytes (tissue macrophages). "Loss-of-function variations in the SLC29A3 gene underlie a group of histiocytic diseases collectively referred to as SLC29A3 disorders, characterized by histiocytosis, hepatosplenomegaly, skin pigmentation, hypertrichosis and type I diabetes." (PMID 40037613, 2025). "Loss-of-function mutations in the lysosomal nucleoside transporter SLC29A3 cause lysosomal nucleoside storage and histiocytosis: phagocyte accumulation in multiple organs." (PMID 37462944, 2023). "In this study, we identified a previously unknown histiocytosis-driving program that is activated by germline loss-of-function mutations in SLC29A3." (PMID 37462944, 2023). "Pathogenic variants in the ENT3 encoding gene SLC29A3 result in different clinical manifestations which correspond to several recessive autosomic disorders previously considered to be distinct, but sharing histiocytosis as a common feature." (PMID 35955904, 2022). "We report two adult siblings with genetically confirmed HS who developed bilateral choroidal infiltration, expanding the phenotypic spectrum of SLC29A3-related histiocytosis." (PMID 41953517, 2026). "New evidence indicates that nucleoside accumulation activates TLR7 and TLR8, promoting histiocytosis in Slc29a3−/− mice and in SLC29A3 disorder patients, respectively." (PMID 40037613, 2025). "As TLR7 and SCL29A3 are both localized to the endosomal compartments, SLC29A3 deficiency results in the accumulation of the TLR7 ligands, Guo, and dGuo, in TLR7-containing compartments, and thereby TLR7 activation drives histiocytosis in Slc29a3−/− mice." (PMID 37462944, 2023). "These SLC29A3 disorders are characterized by histiocytosis: mononuclear phagocyte accumulation in multiple organs." (PMID 37462944, 2023). "We generated Slc29a3‒/‒Tlr7‒/‒ mice to evaluate the role of TLR7 in histiocytosis." (PMID 37462944, 2023). "We hypothesized that Guo, dGuo, and Urd accumulate in the compartments where TLR7 and TLR8 are localized and activate TLR7 and TLR8 to drive histiocytosis in SLC29A3 disorders." (PMID 37462944, 2023). "In SLC29A3 disorders, histiocytosis accompanies inflammation." (PMID 37462944, 2023).
insulin-dependent diabetes (11 papers, 2010 to 2025). "Moreover, our patients presented a few of the non-granulomatous clinical phenotypes previously reported in patients with SLC29A3 mutations, such as insulin-dependent diabetes and finger contracture for P1." (PMID 22238637, 2012). "With the exception of insulin-dependent diabetes and mild finger and toe contractures in one sibling, the two patients with nasal granulomatous histiocytosis studied here displayed none of the many SLC29A3-associated phenotypes." (PMID 22238637, 2012). "A novel homozygous frame-shift mutation c.307-308delTT (p.Phe103fs) in exon 3 of SLC29A3 gene was identified in a 35 years old man with profound hearing loss, camptodactyly, rheumatoid arthritis and delayed puberty without any skin changes, short stature and insulin dependent diabetes mellitus." (PMID 31464584, 2019).